SERGEF (secretion regulating guanine nucleotide exchange factor)
Description:
Probable guanine nucleotide exchange factor (GEF), which may be involved in the secretion process.
Synonyms: DelGEF; GNEFR
Tractability: PROTAC: ubiquitination databases record sites on it.
Gene: Protein-coding gene on chromosome 11 (17,788,043 to 18,013,047, reverse strand). Ensembl gene ENSG00000129158.
Subcellular location: Cytoplasm; Nucleus
Subcellular location (Human Protein Atlas): Nucleoplasm; Cytosol
Gene Ontology:
Molecular function: protein binding; guanyl-nucleotide exchange factor activity
Biological process: negative regulation of protein secretion; signal transduction
Cellular component: cytoplasm; cytosol; nucleoplasm; nucleus
Genetic constraint (gnomAD): Loss-of-function variants: 30 observed, 36.95 expected, observed/expected ratio (o/e) 0.81, 90% interval 0.61 to 1.1. The upper end of that interval is the gene's LOEUF score, 1.1, which puts it in group 4 of 6, group 1 being the genes least tolerant of losing a copy. Missense variants: 447 observed, 486.72 expected, observed/expected ratio (o/e) 0.92, 90% interval 0.85 to 0.99. Synonymous variants: 177 observed, 190.77 expected, observed/expected ratio (o/e) 0.93, 90% interval 0.82 to 1.05.
Homologues: Orthologues: chimpanzee SERGEF (98% identical), macaque SERGEF (95% identical), dog SERGEF (82% identical), pig SERGEF (79% identical), mouse Sergef (74% identical), rabbit SERGEF (70% identical), rat Sergef (63% identical), guinea pig SERGEF (53% identical), zebrafish sergef (43% identical), tropical clawed frog abcf2 (42% identical), Drosophila melanogaster CG7420 (26% identical), Drosophila melanogaster ca (22% identical), and 2 more. Paralogues in human: RCBTB1 (25% identical), RCBTB2 (25% identical), RPGR (22% identical), RCC2 (20% identical), ALS2 (20% identical), RCC1L (18% identical), HERC1 (18% identical), RCC1 (17% identical), RCCD1 (11% identical).
Diseases named in the same sentence as SERGEF in open-access papers:
SERGEF is named in the same sentence as 4 diseases in open-access papers, as found by Europe PMC text mining. Sharing a sentence is not in itself a finding about the gene and the disease. The quoted sentences say what the papers report.
atherosclerosis (2 papers, 2017 to 2020). A disease characterized by the build-up of fatty material and calcium deposition in the arterial wall resulting in partial or complete occlusion of the arterial lumen. "The admixture association of the SERGEF gene in the HIV-positive women provides further support for the role of this gene in atherosclerosis." (PMID 29206233, 2017). "We speculate that lower cCIMT associated with SERGEF in the HIV-positive women may be a result of immunosuppression because of ART or HIV itself or in conjunction with the gene as it appears to mediate atherosclerosis through immune-related mechanisms." (PMID 29206233, 2017). "Among these genes, only STAU1, SERGEF, and PDGFD are known to be associated with atherosclerosis." (PMID 33381146, 2020).
osteoarthritis (1 paper, 2014). A noninflammatory degenerative joint disease occurring chiefly in older persons, characterized by degeneration of the articular cartilage, hypertrophy of bone at the margins and changes in the synovial membrane. "These include genes associated with cartilage formation (SOX6), inflammation and osteoarthritis (SAA) and muscle cell differentiation and muscle regeneration (MYOD1, SERGEF)." (PMID 25270232, 2014).
SERGEF also shares sentences with these, for which no sentence is quoted: Allergy (1 paper); papillary thyroid carcinoma (1).